ST8SIA2 (ST8 alpha-N-acetyl-neuraminide alpha-2,8-sialyltransferase 2)
Diseases named in the same sentence as ST8SIA2 in open-access papers (continued):
Sharing a sentence is not in itself a finding about the gene and the disease.
mental disorder (11 papers, 2012 to 2024). A disease that has its basis in the disruption of mental process. "Loss of St8sia2 in mice by conventional knockout leads to several neuropathological traits with links to psychiatric disorders." (PMID 35115485, 2022). "Alterations in the structure of polysialic acid (polySia/PSA) due to genetic alterations in ST8SIA2, which encodes a polySia-synthesizing enzyme, are related to certain mental disorders." (PMID 31289315, 2019). "There is growing genetic evidence of the involvement of ST8SIA2 (also known as SIAT8B or STX) in conferring risk to mental illness." (PMID 24651862, 2014). "We propose that ST8SIA2 is a generalised susceptibility gene for mental illnesses with neurodevelopmental origins." (PMID 22693595, 2012). "In addition to rare and highly deleterious variants, common variants that have a more subtle effect on ST8SIA2 function are also plausible candidates for contributing to increased risk of mental illness by regulating the timing and level of gene expression." (PMID 24651862, 2014). "The ST8SIA2 gene is also reported to be a generalized susceptibility marker for psychotic and mood disorders on chromosome 15q25-26, and is associated with an increased risk of mental illness, such as autism." (PMID 23675315, 2013). "Functionally, ST8SIA2 is an attractive candidate for mental illnesses with neurodevelopmental pathology." (PMID 22693595, 2012). "Hence, characterisation of the nucleotide variation in ST8SIA2 in patients with a variety of mental illnesses is an important step in understanding the molecular mechanisms through which this gene increases disease risk." (PMID 24651862, 2014). "Moreover, genome-wide studies among normal individuals and patients with mental disorders reveal that ST8SIA2 may be a candidate gene for ASD." (PMID 35957920, 2022).
autism spectrum disorder (9 papers, 2012 to 2024). A spectrum of developmental disorders that includes autism, and Asperger syndrome. "Some population and animal studies have indicated an association between the ST8SIA2 gene and autism spectrum disorder (ASD)." (PMID 35957920, 2022). "Genetic association or linkage with ST8SIA2 has also been observed in patients with major depressive disorder and autism spectrum disorder." (PMID 26418860, 2015). "Interestingly, a recent GWAS for autism spectrum disorder using 1314 families with the verbal subtype identified a significant signal (P = 5.37×10−8) for rs3784730 in intron 4 of ST8SIA2, which lies 3.4 kb from our associated single SNP marker rs2168351." (PMID 22693595, 2012). "In children with autism spectrum disorder, ST8SIA2 gene expression levels were decreased compared to age- and sex-matched controls." (PMID 38529039, 2024). "Reported in a patient with behavioral disorders, epilepsy and autism spectrum disorders, St8sia2 was expressed in the developing brain, and it showed to play an important role in neuronal migration, axon guidance, and synaptic plasticity." (PMID 36279395, 2022). "Furthermore, a 520 kb hemizygous deletion of three genes including ST8SIA2 has been identified in a patient with autism spectrum disorder." (PMID 24651862, 2014).
autism (8 papers, 2012 to 2024). Persistent deficits in social interaction and communication and interaction as well as a markedly restricted repertoire of activity and interest as well as repetitive patterns of behavior. "Thereby, ST8SIA2 gene expression levels negatively correlated with the childhood autism rating scale (CARS) score, indicating more serious stereotype behaviors and sensory abnormalities with decreasing ST8SIA2 expression." (PMID 38529039, 2024).
depression (4 papers, 2012 to 2021). "An association study of 15q25-26 for recurrent early onset depression showed nominal association with NTRK3 and the genes flanking ST8SIA2: SLCO3A1 and C15orf32; but not ST8SIA2 itself." (PMID 22693595, 2012).
neuroblastoma (4 papers, 2021 to 2024). Neuroblastoma (NB) is the most common solid, extracranial childhood tumor. "ST8SIA2 was involved in the developmental regulation of polysialic acid and modulated neuroblastoma adhesion and metastasis." (PMID 36605200, 2022). "On the other hand, ST8SIA2 is an oncogene associated with aggressive disease and poor clinical prognosis in different cancers, including small cell lung cancer (SCLC), pancreatic cancer, and neuroblastoma." (PMID 36703136, 2023). "Interestingly, mRNA levels of ST8SIA2 were highest in stages 1 and 4s neuroblastoma." (PMID 36605200, 2022). "Similar results, regarding decrease of ST8Sia2 expression and polySia were obtained with SH-SY5Y, a human neuroblastoma cell line, after 48 h of T. cruzi infection." (PMID 39321148, 2024).
glioma (3 papers, 2016 to 2023). A benign or malignant brain and spinal cord tumor that arises from glial cells (astrocytes, oligodendrocytes, ependymal cells). "Furthermore, the polysialyltransferase ST8SIA2 is also implicated in small cell lung cancer and glioma metastasis and invasion." (PMID 36605200, 2022).
Anxiety (2 papers, 2022). Intense feelings of nervousness, tension, or panic often arise in response to interpersonal stresses. "It therefore seems reasonable to assume that glutamatergic deficits of MB connectivity in mice with conventional or cKO of St8sia2 are linked to their reduced anxiety-like behavior in the elevated plus maze." (PMID 35115485, 2022). "Altered fear behavior, increased aggression, reduced anxiety, and deficits in social interactions are other behavioral traits of St8sia2-deficient mice." (PMID 35617589, 2022).
bladder cancer (1 paper, 2023). "Among the 412 bladder cancer samples, 42 (10.19%) experienced mutation in the 8 SiaTs which were ST6GALNAC1, ST3GAL6, ST8SIA2, ST6GAL2, ST6GAL1, ST6GALNAC5, ST6GALNAC3, and ST3GAL5." (PMID 37968767, 2023).
breast carcinoma (1 paper, 2016). "Among these, the expression of ST6GALNAC5, ST8SIA3 and ST8SIA4 was significantly upregulated in breast cancer tissues compared with adjacent tissues, and ST8SIA2 and ST8SIA6 were upregulated in the adjacent tissues." (PMID 28032858, 2016).
developmental delay (1 paper, 2019). "We further backcrossed to B6 and found an increased ratio of mice exhibiting abnormal development (e.g., developmental delay and hydrocephalus) (Fisher’s exact test, P = 0.145) and significantly decreased lifespan in the adult St8sia2 homozygous null mutant mice (one-way ANOVA, P < 0.001)." (PMID 31541165, 2019).
Hydrocephalus (1 paper, 2019). Hydrocephalus is an active distension of the ventricular system of the brain resulting from inadequate passage of CSF from its point of production within the cerebral ventricles to its point of absorption into the systemic circulation. "Taken together, these data demonstrate that B6-derived flanking regions near the St8sia2 locus play an important role in hydrocephalus and embryonic lethality." (PMID 31541165, 2019). "We hypothesize that the absence of ST8SIA2 may lead to capillary abnormalities, leading to hydrocephalus and embryonic lethality through internal bleeding." (PMID 31541165, 2019).
non-small cell lung carcinoma (1 paper, 2021). A group of at least three distinct histological types of lung cancer, including non-small cell squamous cell carcinoma, adenocarcinoma, and large cell carcinoma. "The increased expression of ST8SIA2, as we observed in glycated BEN-MEN-1 cells, plays a role in the invasive behavior and was significantly associated with the risk of relapse in non-small-cell lung carcinoma." (PMID 34943806, 2021).
cancer (8 papers, 2021 to 2026). A tumor composed of atypical neoplastic, often pleomorphic cells that invade other tissues. "Another study conducted with Cancer Stem Cells (CSCs), the primary cause of cancer recurrence and metastasis, found ST8SIA2 to be hypermethylated in ESCC-CSCs." (PMID 36547200, 2022). "The ST8SIA2 gene expression data are consistent with the reported prevalence of dPSA-linked cell surface nucleolin in human cancers." (PMID 34544457, 2021). "ST8Sia2 was upregulated in a subset of primary human carcinoma-associated fibroblasts (CAFs), and ST8SIA2 silencing in co-cultured CAFs resulted in decreased lung tumor cells invasion in a 3D model." (PMID 34975914, 2021). "Our analysis also revealed a candidate peptide from ST8SIA2, a gene overexpressed across cancers that participates in tumor invasiveness." (PMID 41477871, 2026). "Despite the known roles of MTHFR and ST8SIA2 in cancer, their links with lncRNAs are under-studied in CRC, indicating a promising avenue for future research." (PMID 39026221, 2024). "Among these, 10 were specifically related to cancer, and MTHFR and ST8SIA2 were predicted to be linked to CRC." (PMID 39026221, 2024). "CMP-Neu5Ac analogues were also shown to exert competitive inhibition against ST8SIA2, blocking ST8SIA2-mediated polysialylation of cancer cells and reducing in vitro migration." (PMID 33921986, 2021). "This study suggests that ST8SIA2 expression and cell surface dPSA are limited to cancer cells and the developing embryo." (PMID 34544457, 2021). "In addition to the cancer cell lines, further evidence for the link between ST8SIA2 and cell surface dPSA-nucleolin was shown with human normal PBMCs, which do not express ST8SIA2 and do not have cell surface dPSA or nucleolin." (PMID 34544457, 2021). "Thus, considering that UL is a benign tumor that share features with malignant tumours, we propose that ST8SIA2 could be considered as a novel molecular target for UL treatment." (PMID 36703136, 2023). "We have also shown that the presence of dPSA-nucleolin on the surface of cancer cells appears to be dependent on re-expression of a fetal polysialyltransferase gene, ST8SIA2, which may indicate a novel cancer pathway to further investigate for additional points of therapeutic intervention." (PMID 34544457, 2021). "We investigated the role of ST8SIA2 and ST8SIA4 related to the production of dPSA on the surface of cancer cells." (PMID 34544457, 2021). "ST8SIA2 is highly expressed during fetal development and in cancer but not in adult normal human cells." (PMID 34544457, 2021). "However, based on RNA-seq data from The Cancer Genome Atlas (TCGA) Program for 37 cancers, most express some level of ST8SIA2 that does not occur in corresponding cells of human normal tissues." (PMID 34544457, 2021).
Tumor (6 papers, 2013 to 2026). "ST8SIA2 correlates with tumour progression in non-small-cell lung cancer and has been linked to tumour invasion and metastasis." (PMID 36077781, 2022). "The expressions of ST8SIA2, 3, and 5 were lower in the tumor samples than in normal tissues." (PMID 38067186, 2023). "Tumor cells highly expressed donor synthesis genes (NANS, CMAS, and the transporter SLC35A1), while the stroma showed enriched expression of sialyltransferases involved in α2-3, α2-6 and α2-8 sialylation (ST3GAL2, ST3GAL5, ST6GAL2, ST6GALNAC5, ST6GALNAC6, ST8SIA1 and ST8SIA2)." (PMID 38594506, 2024).
infection (1 paper, 2024). The state of being infected such as from the introduction of a foreign agent such as serum, vaccine, antigenic substance or organism. "Among the regulated glycogenes, ST8 alpha-N-acetyl-neuraminide alpha-2,8-sialyltransferase 2 (ST8Sia2) was downregulated in T. cruzi-infected hiPSC-CM, being more pronounced at 24 and 48 hours post-infection (h.p.i.)." (PMID 39321148, 2024).
ST8SIA2 also shares sentences with these, for which no sentence is quoted: epilepsy (2 papers); Alzheimer disease (1); behavioral disorders (1); benign tumor (1); Cognitive impairment (1); cystic fibrosis (1); lung carcinoma (1); mental retardation (1); mood disorder (1); neurodegenerative disease (1); neurodevelopmental disorder (1); pancreatic cancer (1); peripheral neuropathy (1); small cell lung carcinoma (1).